NLRP3 (NLR family pyrin domain containing 3)
Diseases named in the same sentence as NLRP3 in open-access papers (continued):
Sharing a sentence is not in itself a finding about the gene and the disease.
depression (continued). "The basic and clinical research for depression has found that NLRP3 inflammasomes are in an activated state, and antidepressant treatment can inhibit the activity of NLRP3 inflammasomes." (PMID 34526897, 2021). "Experiments have shown that NLRP3 inflammatory bodies can mediate hippocampal neuroinflammation and depression-like behavior induced by chronic stress through GR-NF-κ B-NLRP3 signal pathway." (PMID 34531719, 2021). "In clinical studies, an increased activity of the NLRP3 inflammasome has been observed in circulating immune cells of patients with major depression." (PMID 33937941, 2021). "Here, we observed the therapeutic effects of Ori on depression by inhibiting NLRP3 inflammasome via activation of autophagy both in LPS-induced depression mice and LPS-treated astrocytes." (PMID 35096901, 2021). "Antidepressant treatment inhibits NLRP3 inflammasome, highlighting the relationship between depression and NLRP3." (PMID 34526897, 2021). "Taken together, these studies indicate that the activation of NLRP3 inflammasome signaling is involved in the pathogenesis of depression and that inflammasome serves as a potential pharmacological target in depression treatment." (PMID 33466877, 2021). "Notwithstanding, the inflammation induced by NLRP3 inflammasome is a key factor in the pathogenesis of depression, which has been validated by both clinical and preclinical findings." (PMID 34559953, 2021). "Some brain penetrable P2X7R antagonists such as BBG and A-438079 have exhibited antidepressant effects in chronic unpredictable mild stress (CUMS) mice model of depression by inhibiting the activation of P2X7/NLRP3/IL-1β pathway." (PMID 33889073, 2021). "Long-term chronic stress can activate NLRP3, producing a corresponding inflammatory response that contributes to the pathogenesis of depression." (PMID 33505499, 2021). "It has been demonstrated that the NLRP3 inflammasome is involved in the pathological processes of anxiety and depression during neuropathic pain conditions." (PMID 35011486, 2021). "Several studies in past have demonstrated the expression of NLRP3 in microglia, astrocytes and neurons, however, in a study of animal models of depressive disorder expression of NLRP3 was reported only in microglia." (PMID 34895246, 2021). "The interleukin-1 beta (IL-1β) and IL-18 levels are increased in the peripheral blood monocytes of patients with major depression due to the activation of NLRP3 inflammasome." (PMID 32328132, 2020). "It was recently shown that NLRP3 inflammasomes participate in stress-induced depression by regulating IL-1β production in serum as well as in the hippocampus." (PMID 32377306, 2020). "The neuroinflammatory activation is used to explain the pathogenesis of depression, which is mediated by the NF-κB pathway and NLRP3 inflammasome activation." (PMID 32328132, 2020). "The suicide ideation of depressive patients is positively correlated with the level of IL-1, suggesting that IL-1 and NLRP3 inflammasomes are mediators of depression induced by psychological stress." (PMID 32166013, 2020). "The activation of NLRP3 inflammasomes plays a key role in the influence of early adverse experience on adult depression." (PMID 32166013, 2020). "Although we both pay attention to the inflammation and depression, this article highlights the microglia and NLRP3 inflammasome in vivo and vitro experiments." (PMID 32922291, 2020). "Compared with wild-type mice, NLRP3 gene knockout mice didn’t exhibit depression-like behaviors in SPT or TST after 4 weeks of CUMS exposure; meanwhile, NLRP3 gene knockout prevented the promotion of IL-1β in serum and hippocampi of CUMS mice." (PMID 33132912, 2020). "The neuroinflammation and NLRP3 inflammasome activation are known to be involved in the pathology of depression." (PMID 32450903, 2020). "NLRP3 inflammasomes are considered important mediators of depression induced by immune activation during stress exposure." (PMID 32166013, 2020).
depression (continued). "It has been reported that the stress-sensitive NLRP3 inflammasome, which is activated in blood cells from depression patients, plays an important role in priming of microglia, such as induced the activation and amplified expression of IL-1β in the CNS." (PMID 32922291, 2020). "Inhibiting the activation of NLRP3 inflammasome plays an important role in the prevention and treatment of depression." (PMID 32328132, 2020). "NLRP3 inflammasome is a bridge between immune activation and stress exposure; the latter promotes the development of depression through the activation of NLRP3 inflammasome." (PMID 32328132, 2020). "Blocking P2X7 receptor and NLRP3 inflammasome activation can restore brain homeostasis and significantly alleviate depression in HFD rats." (PMID 32166013, 2020). "Increased expression and activity of the NLRP3 inflammasome machinery in circulating immune cells of patients affected by depression, bipolar disorder, and ASD, have been reported." (PMID 33362788, 2020). "It has also been shown that NLRP3 is activated in mononuclear cells in patients with depressive disorder and that some antidepressants compounds seem to show a decrease in NLRP3 activation." (PMID 33329109, 2020). "NLRP3, mostly expressed in microglia, has been reported to be engaged in animal models of depression and patients with MDD." (PMID 32513185, 2020). "A previous study has reported that the expression of NLRP3 is restricted to microglia in a study of animal models of depressive disorder." (PMID 32635937, 2020). "The previous study investigated the mechanism of BA on CUMS induced depression by mediating NLRP3 inflammasome in prefrontal cortex of rats." (PMID 30658416, 2019). "Studies with animal models also provide evidence to the involvement of NLRP3 in the neurobiology of depression." (PMID 31174279, 2019). "Local injection of NPY into the medial prefrontal cortex (mPFC) ameliorated the depression-like behaviors and suppressed the NLRP3 inflammasome signaling pathway." (PMID 31736656, 2019). "There are limited in vivo and clinical studies that implicate contribution of NLRP3 inflammasome activation in the pathogenesis of depression." (PMID 31327964, 2019). "NPY played an antidepressant role in the mPFC by suppressing the NLRP3 signaling pathway, mainly via Y2R, in the LPS-induced depression model rats." (PMID 31736656, 2019). "Emerging evidence reinforces the importance of NLRP3 inflammasome in neuropsychiatric disorders, particularly in depression and anxiety." (PMID 31263417, 2019). "All these results suggest that NPY and Y2R in the mPFC are involved in the pathophysiology of depression and NPY plays an antidepressant role in the mPFC mainly via Y2R, which suppresses the NLRP3 signaling pathway, in LPS-induced depression model rats." (PMID 31736656, 2019). "Caspase-1 and NLRP3 mRNA levels are increased in the blood cells of depressed patients, suggesting that inflammasomes are a key mediator in the development of depression." (PMID 31439031, 2019). "NLRP3 inflammasome activation is observed in animal models of depression as well as in depressive patients." (PMID 31555091, 2019). "To further clarify the roles of NF-κB and the NLRP3 inflammasome in depression, we inhibited NF-κB and knocked out the NLRP3 gene in vitro." (PMID 31555091, 2019). "Consistent with previous study, activated NLRP3 inflammasomes in microglia are involved in CMS-induced depression-like behavior in rats." (PMID 31555091, 2019). "In a case–control study, 20 patients with major depressive disorder exhibited high anxiety score and increased levels of caspase-1 and NLRP3 expression in peripheral blood mononuclear cells than did the healthy group." (PMID 31263417, 2019). "Using a mouse model of depression, it was reported that several antidepressants not only reduce depression-like behavior, but also inhibit the NLRP3-inflammasome in an autophagy-dependent manner." (PMID 30642024, 2019).
depression (continued). "Recently, a pivotal role in the pathogenesis of depression has been assigned to the activation of the brain Nod-like receptor pyrin-containing 3 (NLRP3) inflammasome." (PMID 30610610, 2019). "Recently, the role of Nucleotide-binding oligomerization domain (NACHT), Leucine-rich repeat (LRR), and Pyrin domation (PYD) domains-containing protein 3 (NLRP3) inflammasome-dependent IL-1β has emerged as a novel contributor to depressive disorders." (PMID 31263417, 2019). "Among the NLR subtypes, the NLR protein 3 (NLRP3) inflammasome has often been studied in the context of CNS inflammation related to stress and depression." (PMID 30174579, 2018). "P2X7R/NLRP3 inflammasome axis has also been demonstrated to link cytokine, psychological stress and depression." (PMID 30390665, 2018). "It raises the possibility that the NLRP3 inflammasome can be a more specific target for the development of novel pharmacological agents for depression treatments in the near future." (PMID 29343269, 2018). "The prefrontal cortex is mostly reported with NLRP3 inflammasome activation by us and others in CUMS rodents, thus becoming a relatively susceptible brain region in depression." (PMID 29853787, 2018). "Recent research has also indicated that activation of NLRP3 inflammasome signaling, a pivotal mediator of IL-1β function, contributes to depression." (PMID 29946236, 2018). "NLRP3 inflammasome activation is observed in mononuclear blood cells of patients with major depression and in brain of chronic unpredictable mild stress- (CUMS-) induced depression in rats by us." (PMID 29853787, 2018). "Activation of NLRP3 has been documented in depression and anxiety and both pharmacological blockade of NLRP3 or gene deletion of NLRP3 reduces depressive behavior and anxiety in animal models of these disorders." (PMID 29410649, 2018). "So far, several agents have been reported to be effective in the alleviation of depression through the inhibition of the NLRP3 inflammasome." (PMID 30233319, 2018). "Here in this review, we will discuss the roles of the NLRP3 inflammasome in several kinds of CNS disorders including cerebrovascular diseases, neurodegenerative diseases, multiple sclerosis, depression, and other CNS disorders such as traumatic brain injury." (PMID 30233319, 2018). "Alcocer-Gómez posited that antidepressants containing fluoxetine show autophagy dependent-NLRP3-inflammasome inhibition in major depressive disorders." (PMID 30349488, 2018). "While depression is tightly related to the hyperactivation of NLRP3 inflammasome and overproduction of IL-1β, autophagy removes aggregated inflammasome structures, thus contributing to dampening proinflammatory responses." (PMID 29212498, 2017). "Our data showed that periphery immune challenge by LPS for 2 weeks successfully induced the rats to a depression-like state, accompanied with enhanced expression of pro-inflammatory cytokines and NLRP3 inflammasome activation." (PMID 29212498, 2017). "Since the NLRP3 inflammasome is one of the convergent pathways common to depression and autophagy, we further investigated the involvement of NLRP3 in the progression and alleviation of depression." (PMID 29212498, 2017). "Collectively, NLRP3 inflammasome activation and subsequent IL-1β generation were involved in the development of depression and T2D separately." (PMID 29084550, 2017). "In support of this concept, increased gene expression of NLRP3 and caspase-1 in the mononuclear blood cells and elevated serum levels of IL-1β and IL-18 have been found in patients with major depression." (PMID 26631274, 2016). "Taken together, these data imply that depression may promote the activation of NLRP3 and subsequent disease progression in immune‐mediated hepatitis." (PMID 41503678, 2026).
depression (continued). "A bibliometric analysis conducted between 2004 and 2023 on neuroinflammation in depression highlighted the NLRP3 inflammasome, microglia, tumor necrosis factor‐alpha (TNF‐α), and brain‐derived neurotrophic factor (BDNF) as central components in the underlying pathogenic mechanisms." (PMID 41479745, 2026). "Studies suggest that modulating the MAPK/NLRP3 signaling axis could be beneficial in inhibiting astrocyte pyroptosis and alleviating symptoms of depression." (PMID 41341504, 2025). "Indeed, different antidepressants alleviate depression-related behaviours by specifically counteracting the NLRP3 inflammasome signalling pathway." (PMID 39005130, 2025). "In addition, inhibition of excessive NLRP3 inflammasome activation to rebalance microglia polarization also has been confirmed as an effective strategy for ameliorating depression-like behaviors." (PMID 40275171, 2025). "Our results showed that FMN significantly reverses depression-like behaviors, alleviates neuroinflammation and neuronal damage, rebalances M1/M2 polarization, inhibits NLRP3 inflammasome and enhances microglial autophagy level in prefrontal cortex of LPS-induced depressive mice." (PMID 40275171, 2025). "However, understanding NLRP3’s contribution in leading different components of disease, particularly in mediating depression-related cognitive impairments and their response to targeted treatment, remains an ongoing investigation." (PMID 39005130, 2025). "This “memory” effect may account for the sustained low-level activation of NLRP3 inflammasome observed in both depression and CVD." (PMID 41194915, 2025). "Elevated NLRP3 mRNA levels have been demonstrated in the blood of people with depression." (PMID 40559778, 2025). "Certain antidepressants alleviate depression-related behavior by counteracting NLRP3 activation." (PMID 39005130, 2025). "Inhibiting the NLRP3 inflammasome also led to decreased mitochondrial reactive oxygen species (mtROS) accumulation and increased mitophagy in vitro, ultimately increasing the clearance of damaged mitochondria in the studied models of depression." (PMID 40868122, 2025). "In conclusion, the MGB axis plays a critical regulatory role in the onset and progression of depression through multiple mechanisms that alter the neuroimmune microenvironment, especially by mediating the aberrant activation of the NLRP3 inflammasome and microglia." (PMID 40936908, 2025). "Knockout UCP2 could lead to the activation of the nod-like receptor protein 3 (NLRP3) inflammasome in hippocampal astrocytes and induce depression-like behaviors in mice." (PMID 40108901, 2025). "Hesperidin (50 mg/kg) in CUMS depressed mice may be effective in the treatment of major depressive disorder by regulating NLRP3-induced pyroptosis." (PMID 40703750, 2025). "In conclusion, we identified PPARα as a direct target of FMN, and our data firstly indicated that FMN ameliorates LPS-induced depression-like behaviors through rebalancing microglia M1/M2 polarization and inhibiting NLRP3 inflammasome, with involvement of activating PPARα-mediated autophagy." (PMID 40275171, 2025). "The activation of NLRP3 and the release of IL-1β and IL-18 may be involved in the pathogenesis of depression through multiple mechanisms." (PMID 40497971, 2025). "Furthermore, NLRP3/caspase-1/GSDMD pathway-mediated pyroptosis can cause psychiatric disorders, such as depression, complicating AA treatment." (PMID 39319843, 2025). "This regulation modulates the MAPK/NLRP3 signaling pathway, suppressing MAPK activity and NLRP3 inflammasome formation, thereby providing insights into its underlying mechanism of action against depression." (PMID 41341504, 2025). "(2022) demonstrated that the antidepressant fluoxetine counteracted isolation-exacerbated brain and cardiovascular pathology in an AD-like depression model by activating Nrf2/HO-1, an antioxidant pathway that limits ROS accumulation and thereby inhibits NLRP3 signaling." (PMID 41357236, 2025).
depression (continued). "In preclinical mouse models, tabersonine effectively inhibits NLRP3 inflammasome-mediated signaling, downregulates pro-inflammatory cytokine expression, inhibits the activation of microglia, and significantly improves LPS-induced depression-like behaviors." (PMID 40936908, 2025). "When NLRP3 is activated by stress, it regulates the activation of caspase-1, which in turn promotes the maturation of IL-1β in microglia, and the overproduction of cytokines in microglia contributes to the development of depression." (PMID 40308754, 2025). "NOD-like receptor of protein 3 (NLRP3) inflammation may be involved in LPS-induced depression-like pathological changes and promote IL-1β secretion and synthesis." (PMID 40520890, 2025). "Inflammatory hematological indicators from a complete blood count (CBC) have even been identified as potential prognostic factors for CVD mortality.Therefore, regulating and intervening in the activation of the NLRP3 inflammasome offers a new perspective for treating CVD-depression comorbidity." (PMID 41194915, 2025). "Upon stimulation, the NLRP3 inflammasome becomes activated, promoting the release of mature inflammatory cytokines, initiating inflammatory responses, and contributing to the development of depression." (PMID 41199561, 2025). "The upregulation of NLRP3 in microglial cells leads to the release of pro‐inflammatory cytokines (such as IL‐1β and IL‐18); this in turn triggers neuroinflammation and neuronal damage, which contributes to the onset and progression of depression." (PMID 40406924, 2025). "Additionally, the NLRP3 inflammasome, a regulator of inflammation, has been linked to depression, and FMT from NLRP3 knockout mice alleviated depression-like behaviors by modulating immune responses and improving astrocyte function." (PMID 40283148, 2025). "Moreover, activated NLRP3 inflammasomes have been identified in both brain tissue and peripheral blood samples from patients with depression, along with an overproduction of inflammatory proteins and proinflammatory cytokines." (PMID 41194915, 2025). "Additionally, gut microbiota can modulate NLRP3 inflammasome involvement in the pathogenesis of depression." (PMID 40936908, 2025). "The NLRP3 inflammasome, a key inflammatory signaling platform of the innate immune system, mediates the maturation and release of IL-1β and IL-18 and induces pyroptosis, playing a significant role in both depression and CVD." (PMID 41194915, 2025). "Magnolol, a natural phenolic compound derived from Magnolia officinalis, alleviates CUMS-induced depression by suppressing pro-inflammatory M1 microglial polarization and promoting anti-inflammatory M2 polarization through the Nrf2/heme oxygenase-1 (HO-1)/NLRP3 signaling pathway." (PMID 40936908, 2025). "Mitochondrial transplantation may, therefore, exert its therapeutic effects on CRS-induced depression by restoring mitochondrial function and suppressing the NLRP3/caspase 1/IL1β signaling pathway." (PMID 40001487, 2025). "New strategies in terms of the development of effective treatments for depression in humans may be to restore microglial homeostasis in the hippocampus and reduce or inhibit NLRP3 inflammasome activation." (PMID 39962033, 2025). "The NLRP3 inflammasome is essential in the pathophysiology of stress-induced depression." (PMID 40281288, 2025). "Furthermore, the NLRP3 inflammasome contributes to LPS-induced depression-like behavior through the induction of indoleamine 2,3-dioxygenase." (PMID 40936908, 2025). "Activation of the NLRP3 inflammasome has been observed in individuals with major depressive disorder, indicating that NLRP3 could serve as a potential novel therapeutic target for managing depressive disorders." (PMID 40281288, 2025). "The NLRP3 inflammasome plays a crucial role in stress-induced depression, suggesting that NLRP3 may represent a novel therapeutic target to cope with depressive illness." (PMID 39962033, 2025).